MYH9 (myosin heavy chain 9)
Diseases named in the same sentence as MYH9 in open-access papers (continued):
Sharing a sentence is not in itself a finding about the gene and the disease.
lupus nephritis (8 papers, 2013 to 2025). Glomerulonephritis in the context of systemic lupus erythematosus. "APOL1 risk alleles were previously associated with ESRD in lupus nephritis patients of African descent, while MYH9 is more relevant in European ancestry populations." (PMID 39857298, 2025). "MYH9 is an apoptotic caspase substrate, and SNPs in the MYH9 gene are associated with increased incidence of lupus nephritis in European-Americans." (PMID 28649187, 2017). "In this study, we evaluated the role of MYH9 and APOL1 gene polymorphisms in the risk of CKD in Brazilian patients with lupus nephritis (LN)." (PMID 24658608, 2014). "The results were maintained after adjusting for the different ancestry covariates, indicating that in this cohort, MYH9, but not APOL1, gene polymorphisms confer an increased risk of CKD in lupus nephritis patients, independently of race." (PMID 39857298, 2025). "The importance of the MYH9 polymorphisms in the context of CKD is that there is enough evidence in the literature of being a causal variant for CKD in diabetics, Lupus Nephritis, and non-diabetic population." (PMID 32765897, 2020). "MYH9- rs3752462 polymorphism by far has produced an impressive association with CKD among diabetics, Lupus Nephritis, and non-diabetic population." (PMID 32765897, 2020). "Lin and co found an association of selected MYH9 SNPs (although not rs3752462) with lupus nephritis occurrence, while in patients included in the already mentioned Corales study MYH8 SNPs did not correlate with lupus nephritis activity." (PMID 32873246, 2020).
ovarian carcinoma (8 papers, 2020 to 2024). A malignant neoplasm originating from the surface ovarian epithelium. "MiR-6089 also targets MYH9 and its overexpression suppresses ovarian cancer cell proliferation, migration, invasion, and metastasis in vivo and in vitro, and miR-6089 negatively correlates with MYH9 expression in clinical samples." (PMID 32660059, 2020). "In ovarian cancer, the miR-6089/MYH9/β-catenin/c-Jun axis acts as a negative feedback loop." (PMID 37854681, 2023). "Moreover, multiple molecules can be observed to regulate cells by crosstalk integrin-related signaling, such as Myosin Heavy Chain 9 (MYH9), Rab11, and Wnt5a, especially the latter, as the paracrine factors involved in EMT/MET have been found to modulate the ITGAV level in ovarian cancer." (PMID 34572451, 2021). "Also, the negative feedback loop of miR-6089/MYH9/β-catenin/c-Jun constrained the growth of ovarian cancer." (PMID 34901459, 2021).
thyroid cancer (8 papers, 2020 to 2023). "Knockdown of Nek6 circRNA has been observed to cause inhibition of the expression of myosin heavy chain 9 (MYH9), allowing differentiated thyroid cancers to become more susceptible to iodine 121-based radiotherapy." (PMID 35409400, 2022). "Since tumor invasion and metastasis are the leading cause of cancer-related death, including thyroid cancer, we tested the effect of MYH9 on PTC cell migration and invasion." (PMID 32982961, 2020). "Although MYH9 binds to lncRNA gene PTCSC2 and regulates FOXE1 in the 9q22 thyroid cancer risk locus, mechanistically, the detailed role of MYH9 in PTC is still unknown." (PMID 32982961, 2020). "MYH9 binds to lncRNA gene PTCSC2 (Papillary Thyroid Carcinoma Susceptibility Candidate 2) and regulates FOXE1 (Forkhead box protein E1) in the 9q22 thyroid cancer risk locus." (PMID 37175943, 2023). "MYH9 acted as a suppressor gene in thyroid cancer by binding to the promoter region of lncRNA PTCSC2 and promoting forehead box E1 activation." (PMID 35318312, 2022). "In PTC, MYH9 binds the lncRNA gene, PTCSC2, to modulate FOXE1 in the 9q22 thyroid cancer risk locus." (PMID 32982961, 2020). "Another such example is lncRNA PTCSC2 which interacts with MYH9 and, thus, reverses MYH9-mediaed inhibition of activities of a bidirectional promoter shared by FOXE1 and PTCSC2 in thyroid cancer." (PMID 37072811, 2023). "In thyroid cancer, lncRNA PTCSC2 has been confirmed to interact with MYH9 to regulate FOXE1 expression." (PMID 35541917, 2022).
acute myeloid leukemia (7 papers, 2017 to 2024). Acute myeloid leukemia (AML) is a group of neoplasms arising from precursor cells committed to the myeloid cell-line differentiation. "Hematologic tumors, such as acute myeloid leukemia (AML), and other malignancies also exhibit high MYH9 expression, contributing to tumor progression through diverse mechanisms." (PMID 39149512, 2024). "However, the prognostic relevance of MYH9 expression in acute myeloid leukemia is still unclear." (PMID 27437869, 2017).
esophageal cancer (7 papers, 2020 to 2025). A primary or metastatic malignant neoplasm involving the esophagus. "MYH9 also serves as a marker and prognostic indicator for esophageal cancer stem cells, promoting tumorigenesis via the PI3K/AKT/mTOR axis." (PMID 39988672, 2025). "Another study suggested that MYH9 significantly activates the PI3K/AKT/mTOR axis in esophagus cancer (EC) cells, promoting tumorigenesis." (PMID 39149512, 2024). "PTP1B promoted cell invasion by increasing EGFR protein expression through MYH9 in esophageal cancer cells." (PMID 36618415, 2022). "MYH9 is closely related to the progression and poor prognosis of gastric and esophageal cancers, suggesting its potential role in promoting cancer." (PMID 35646686, 2022). "Moreover, down-regulating the MYH9 expression inhibited angiogenesis, migration, and invasion of esophageal cancer cells." (PMID 32788880, 2020). "Our results demonstrated that MYH9 protein showed strong cytoplasm staining in esophageal carcinoma tissues whereas nearly negative in matched normal tissues." (PMID 32788880, 2020). "In vitro, the results of western blot analysis showed that knockdown of MYH9 abrogated the alteration of the expression of β‐catenin/c‐Myc pathway biomarkers regulated by PGK1‐overexpression, and there was no obvious effect of PGK1 overexpression on MYH9 expression in esophageal cancer cells." (PMID 40534132, 2025).
head and neck cancer (7 papers, 2017 to 2023). A primary or metastatic malignant neoplasm affecting the head and neck. "This study deciphered the molecular function of MYH9 in head and neck cancer (HNC)." (PMID 36139430, 2022).
immune thrombocytopenia (7 papers, 2012 to 2024). "This section emphasizes the misdiagnosis of MYH9-RDs as immune thrombocytopenia due to overlapping clinical features." (PMID 38134071, 2023). "Here, we report the case of a 46-year-old Chinese woman with MYH9-RD who was primarily misdiagnosed with idiopathic thrombocytopenia purpura." (PMID 34394193, 2021). "As a consequence, a significant number of patients with MYH9‐RD are initially misdiagnosed as immune thrombocytopenic purpura (ITP), and thus subjected to ineffective and potentially harmful treatments, or classified as inherited platelet disorder of unknown origin." (PMID 31562665, 2020). "Often misdiagnosed as idiopathic thrombocytopenic purpura (ITP), MYH9-RD requires accurate identification to avoid inappropriate treatments like steroids, rituximab, or splenectomy." (PMID 38550428, 2024).
liver cancer (7 papers, 2022 to 2025). An epithelial or non-epithelial malignant neoplasm that arises from the liver. "Notable examples include circ-EIF6, encoding the peptide EIF6-224aa31 through IRES-driven translation, which interacts with MYH9 to activate the Wnt/β-catenin pathway, and circZKSCAN1, which enhances sorafenib sensitivity in liver cancer." (PMID 40713830, 2025). "We measured the expression level of p-MYH9 in 11 liver cancer cell lines, and calculated the IC50 values of the HCC cell lines for lenvatinib by CCK-8 detection." (PMID 39300073, 2024). "In order to explore the specific regulatory relationship between TM4SF1 and MYH9 in liver cancer cells, we silenced TM4SF1 and MYH9 respectively, and observed the expression of another molecule by WB experiment." (PMID 37069693, 2023). "We also reached a consistent conclusion in our study that MYH9 plays a promoting role in liver cancer." (PMID 36374212, 2022). "Liver cancer-related data show that Myh9 may promote the dryness of liver cancer and accelerate cancer progression through Wnt signaling." (PMID 36374212, 2022).
nephrotic syndrome (7 papers, 2009 to 2025). A collection of symptoms that include severe edema, proteinuria, and hypoalbuminemia; it is indicative of renal dysfunction. "Nevertheless, MYH9 mutations can cause a monogenic disease with kidney involvement, and MYH9 rs3752462 was considered an independent risk factor for CKD, nephrotic syndrome, and ESRD in case-control studies from different populations." (PMID 39857298, 2025). "Furthermore, proteomic analysis revealed the significant potential of MYH9 in early prediction of GCR childhood nephrotic syndrome, positioning it as a potential candidate biomarker for evaluating glucocorticoid efficacy." (PMID 38162645, 2023). "Likewise, the dysregulation of pathways including glomerulonephritis and Genes controlling nephrogenesis (ITGB1), Nephrin/Neph1 signaling in the kidney podocyte (RAC1), and Nephrotic syndrome (MYH9) were also determined in this study due to the cytotoxicity effect of MWCNT." (PMID 35176998, 2022).
osteosarcoma (7 papers, 2021 to 2025). A usually aggressive malignant bone-forming mesenchymal neoplasm, predominantly affecting adolescents and young adults. "High expression of MYH9 in osteosarcoma tissues showed a clear association with a higher Enneking classification (III classification) and the presence of lung metastasis." (PMID 37892851, 2023). "Mechanistically, MRPL23-AS1 competed with miR-30b and increased the expression of myosin heavy chain 9 (MYH9), thus activating the Wnt/β-catenin signaling pathway and promoting osteosarcoma progression." (PMID 39682098, 2024). "Downregulation of MYH9 expression effectively impaired the migration and invasion capabilities of osteosarcoma cell line SAOS2 cells." (PMID 37892851, 2023). "In conclusion, our study introduces and validates a unique prognostic signature based on two DRGs (MYH9 and LRPPRC) for osteosarcoma." (PMID 37892851, 2023). "Recent research on osteosarcoma has suggested that lncRNA MRLP23-AS1 might be overexpressed and act as a sponge for miR-30b, so that the miR-30b inhibitory effect on its target mRNA (myosin heavy chain 9, MYH9) is reduced to provoke an increase of the final level of this protein." (PMID 36289882, 2022).
Papillary Thyroid Carcinoma (7 papers, 2014 to 2024). "Recent evidence suggests that myosin-9 (MYH9) is a binding partner of the papillary thyroid cancer susceptibility candidate 2 (PTCSC2) long noncoding RNA." (PMID 28635633, 2017). "MYH9 inhibits the activity of the bidirectional promoter shared by Forkhead Box E1 (FOXE1) and the lncRNA gene papillary thyroid carcinoma susceptibility candidate 2 (PTCSC2)." (PMID 39273383, 2024). "CRLF1 interacts with MYH9 to promote cell proliferation and metastasis via the ERK/ETV4 axis in papillary thyroid carcinoma." (PMID 37875476, 2023). "In differentiated thyroid carcinoma (DTC), MYH9 contributes to radioresistance." (PMID 39273383, 2024).
lung adenocarcinoma (6 papers, 2015 to 2024). A carcinoma that arises from the lung and is characterized by the presence of malignant glandular epithelial cells. "As a transporter, MYH9 is important for MICAL2-mediated malignancy in patients with lung adenocarcinoma." (PMID 39273383, 2024). "In lung adenocarcinoma, MYH9 stabilizes c-Myc via deubiquitination with the help of the deubiquitinating enzyme ubiquitin-specific peptidase 7 (USP7) to promote cell cycle progression and EMT signaling." (PMID 39273383, 2024). "Although some studies have shown that the expression of MYH9 is related to the histological characteristics of lung adenocarcinoma, more evidence is needed to prove its therapeutic value in patients with NSCLC." (PMID 34635641, 2021).
anaplastic large cell lymphoma (5 papers, 2013 to 2024). Anaplastic large cell lymphoma (ALCL) is a rare and aggressive peripheral T-cell non-Hodgkin lymphoma, belonging to the group of CD30-positive lymphoproliferative disorders, which affects lymph nodes and extranodal sites. "In the case of anaplastic large cell lymphoma, the genes linked to protein crotonylation are moesin (MSN), myosin heavy chain 9 (MYH9), and myosin heavy chain 10 (MYH10)." (PMID 39513918, 2024). "MYH9 fusion proteins have been found in anaplastic large cell lymphoma and one example is the MYH9-ALK fusion protein that has tyrosine kinase activity in vivo." (PMID 27822437, 2016). "A chimeric MYH9-Alk transcript formed by the fusion of MYH9 and ALK (anaplastic lymphoma kinase) was observed in anaplastic large cell lymphoma but its disease relevance is yet to be established." (PMID 25072053, 2014).
glioblastoma (5 papers, 2021 to 2025). The most malignant astrocytic tumor (WHO grade IV). "It has been reported that MYH9 is deregulated in glioblastoma (GBM) serum small extracellular vesicles and is associated with GBM progression and metastasis." (PMID 34887392, 2021). "The inhibitory effects of CBX7 on glioblastoma cell proliferation, migration, invasion, and stemness are reversed following MYH9 overexpression." (PMID 39988672, 2025). "In 2021, Yao and colleagues reported that overexpression of Thrombospondin 1 (THBS1) promotes the proliferation, migration, and invasion of glioblastoma cells, while knockdown of MYH9 reverses these effects." (PMID 39988672, 2025). "Here, we reveal that CBX7 interacts with MYH9 to promote its degradation, thereby inhibiting glioblastoma cell stemness." (PMID 39988672, 2025). "In this study, we found that CBX7 interacts with MYH9, with Ring1A/B acting as E3 ligases, promoting MYH9 degradation through the ubiquitin-proteasome pathway in glioblastoma." (PMID 39988672, 2025). "We conducted mass spectrophotometry analysis of glioblastoma cells and identified MYH9 as a novel regulatory target of CBX7." (PMID 39988672, 2025). "In summary, these results suggest that CBX7 inhibits the stemness phenotype of glioblastoma cells by downregulating MYH9." (PMID 39988672, 2025). "Here we reveal that CBX7, as part of the PRC1 complex, promotes MYH9 ubiquitination and degradation, thereby inhibiting the glioblastoma stem cell phenotype, with Ring1A/B serving as E3 ligases." (PMID 39988672, 2025). "mTORC2-associated interactome showed actin-binding proteins and microtubule-associated proteins significantly changed depending on mTORC2 activity level in glioblastoma, including Myosin-9/MYH9, Plectin/PLEC and MAP1B." (PMID 36552831, 2022). "Additionally, we have demonstrated for the first time that CBX7, as part of the PRC1 complex, promotes MYH9 ubiquitination and degradation, inhibiting stemness, migration, invasion, and colony formation in glioblastoma cells." (PMID 39988672, 2025). "We then overexpressed MYH9 in U251 and LN229 cells and found that MYH9 could promote the proliferative and sphere-forming ability of glioblastoma cells." (PMID 39988672, 2025). "Our results show that MYH9 drives the NF-κB signaling pathway to promote glioblastoma progression." (PMID 39988672, 2025). "Furthermore, overexpression of MYH9 in glioblastoma cells reverses the inhibitory effects of CBX7 on migration, proliferation, invasion, and stemness of glioblastoma cells." (PMID 39988672, 2025). "We show that CBX7 promotes the degradation of myosin heavy chain 9 (MYH9) protein through the ubiquitin-proteasome pathway via the polycomb repressive complex 1 (PRC1) and suppresses the stem-like phenotype of glioblastoma cells by inhibiting the nuclear factor kappa-B (NF-κB) signaling pathway." (PMID 39988672, 2025).
lymph node metastasis (5 papers, 2020 to 2023). "On the other hand, lower expression of the CSC-associated genes ALDH1A3, LGALS3 and MYH9 and the pluripotency gene POU5F1 assessed by fingerprint values, were instead associated with the presence of lymph node metastases (LN Met)." (PMID 38124067, 2023). "Simultaneously, univariate regression analysis showed that in addition to the expression of MYH9, the patient’s age, lymph node metastasis, and clinical stage were also related to the overall survival time." (PMID 34635641, 2021). "Moreover, the MYH9 expression level is related to lymph node metastasis." (PMID 32788880, 2020).
Obesity (5 papers, 2023 to 2025). Accumulation of substantial excess body fat. "HMBA ameliorates obesity by MYH9- and ACTG1-dependent regulation of hypothalamic neuropeptides." (PMID 39408647, 2024). "The network of upregulated proteins demonstrated a dense interaction architecture with KRT1 and MYH9 emerging as key hub nodes, suggesting their potential core roles in the functional transformation of VAT in obesity." (PMID 40822952, 2025). "We found that HMBA bound to MYH9 and ACTG1, which were required for the anti‐obesity effects of HMBA in both NPY‐expressing and POMC‐expressing neurons." (PMID 37984341, 2023). "Collectively, the reducing effects of HMBA on body weight and food intake were completely abrogated by silencing of Myh9 and Actg1 in AgRP and POMC neurons, suggesting that MYH9 and ACTG1 are required for the anti‐obesity effects of HMBA." (PMID 37984341, 2023).
platelet disorders (5 papers, 2017 to 2025). "We also describe the phenotypic profiles of this MYH9‐RD cohort, adding new insight into genotype–phenotype correlations and expanding the knowledge of this rare inherited platelet disorder." (PMID 31562665, 2020). "Our results confirm the clinical heterogeneity of MYH9‐RD and show that, in the presence of an unclassified platelet disorder with macrothrombocytes, MYH9‐RD should always be considered." (PMID 31562665, 2020). "Interestingly, patients in whom the diagnosis of MYH9-related platelet disorders or BSS were confirmed by molecular or flow cytometry assays presented significantly higher IPF values than patients with a diagnosis of non-specified HMT." (PMID 28611471, 2017).
triple-negative breast carcinoma (5 papers, 2022 to 2025). An invasive breast carcinoma which is negative for expression of estrogen receptor (ER), progesterone receptor (PR), and human epidermal growth factor receptor 2 (HER2). "Circ-EIF6, encoding the novel peptide EIF6-224aa, enhances proliferation and metastasis of triple-negative breast cancer cells by activating the MYH9/Wnt/β-catenin pathway." (PMID 38383479, 2024). "CircRNA EIF6-224aa directly interacts with the MYH9 protein and impedes MYH9 degradation by suppressing the ubiquitin-proteasome pathway, subsequently activating the Wnt/beta-catenin signalling pathway in triple-negative breast cancer." (PMID 37875476, 2023). "In triple-negative breast cancer, circRNA EIF6-224aa directly interacts with MYH9, inhibiting MYH9 degradation through the ubiquitin-proteasome pathway and activating the Wnt/β-catenin signaling pathway." (PMID 39988672, 2025). "Our analyses revealed that the relapse-free survival (RFS) of BRCA, HER2 positive, luminal A, and luminal B did not significantly correlate with MYH9 expression except for triple-negative breast cancer (TNBC) (p = 0.029)." (PMID 35453742, 2022).